RN7SL274P (RNA, 7SL, cytoplasmic 274, pseudogene)
Synonyms: RN7SL694P
Gene: Miscellaneous RNA gene on chromosome 16 (14,601,823 to 14,602,094, reverse strand). Ensembl gene ENSG00000242430.
Homologues: Orthologues: chimpanzee Metazoa_SRP (99% identical). Paralogues in human: RN7SL811P (80% identical), RN7SL134P (79% identical), Metazoa_SRP (79% identical), RN7SL371P (79% identical), RN7SL784P (79% identical), RN7SL96P (79% identical), Metazoa_SRP (78% identical), RN7SL391P (78% identical), RN7SL470P (78% identical), RN7SL596P (78% identical), RN7SL774P (78% identical), RN7SL163P (78% identical), and 707 more.